CD4 (CD4 molecule)
Diseases named in the same sentence as CD4 in open-access papers (continued):
Sharing a sentence is not in itself a finding about the gene and the disease.
tumor (continued). "Cell depletion using antibodies against CD4, CD8, and NK1.1 in the MC38 tumor model showed that the therapeutic efficacy of this IL-36γ-armed OV depended on both CD4+ and CD8+ T cells, and partially on NK cells." (PMID 33538860, 2021). "Neo-adjuvant RFA of NSCLC tumours showed prominent CD8 and CD4 T cell infiltration in the peripheral regions of RFA-treated tumours as well as increased frequency of pro-inflammatory BDCA-3+ DCs in peripheral blood suggesting systemic immune activation." (PMID 34733287, 2021). "The results showed that the percentage of Th1 cells (CD4+T-bet+) was upregulated after RFA and cryo-thermal therapy compared to the tumor-bearing control, but the level of Th1 cells after cryo-thermal therapy was much higher than that after RFA treatment." (PMID 34576115, 2021). "The number of CD4+ effector T cells and CD8+ cytotoxic T cells, and CD8+/PD-1+ tumor-infiltrating lymphocytes (TIL) tended to be smaller, especially in stromata of HPD group." (PMID 33402127, 2021). "Significantly higher percentages of tumor-infiltrating CD103+ T cells were CD8+ (mean 62.0%) than CD4+ (mean 34.8%, p<0.0001), CD4+FOXP3+ (mean 1.4%, p<0.0001) and CD4+FOXP3− (33.0%, p=0.0009)." (PMID 33479027, 2021). "Of note, we have previously demonstrated that dual deficiency for PARP-1 and PARP-2 in T cells results in a significant decrease of both CD4 and CD8 peripheral T cells and consequently impairs the T cell response to tumours." (PMID 34885119, 2021). "Summing up the clinical data that exists on anti-tumor vaccines so far, these vaccines have proven safe and moderately effective, inducing a CD8+- and CD4+-specific T cell response, but more research on this is warranted in the future." (PMID 34885082, 2021). "And the PLP group had more IFN-γ-expressing CD4+ T cells in inguinal lymph node and spleens and more IFN-γ-expressing CD8+ T cells in inguinal lymph node, spleen, and tumor as compared with the control group mice." (PMID 34504423, 2021). "Antibody-mediated T cell depletion revealed that both CD4+ and CD8+ T cell subsets were necessary to reject the tumor indicating that the antitumor effect of artLCMV-TRP2 treatment was mediated by TRP2-specific T cells." (PMID 34354077, 2021). "Initial results demonstrated that this antibody targeted CD4+ T cells, increasing their effector functions by releasing cytolytic granzyme B and interferon (IFN)-γ, followed by complete suppression of tumor growth." (PMID 34439292, 2021). "Overall, these data show that the expression of Ccr8 within the LLC-OVA tumor immune compartment is restricted to a subset of Tregs, but also to populations of dysfunctional CD8+ and CD4+ T cells." (PMID 33589525, 2021). "Human B cells can efficiently present peptides to CD4 + T cells after activated by CD40 ligand and pulsed with tumor antigens." (PMID 34118931, 2021). "In WT mice, epigenetic therapy increased the number of tumor CD8+ T cells and increased the proportion of CD4+ T cells expressing IFN‐γ and TNF‐α." (PMID 33480449, 2021). "Dysfunctional and (terminally) exhausted CD4+ and CD8+ T cells as well as tumoral DCs are characterized by overexpression of TIM-3, which is likely related to tumor cell invasion, metastatic processes and recurrence." (PMID 34439292, 2021). "In GBM-bearing mice, vaccination with mDCs resulted in type 1 T-helper (Th1) immune response and infiltration of CD4+ and CD8+ T-cells, leading to tumor elimination and prolonged survival." (PMID 34715891, 2021). "Expanding our view of CD4+ TH1 and TH2 cells, there are some less explored TH cell subsets which have unique potential in adaptive anti-tumor immunity." (PMID 34012451, 2021). "Lymphocytes are closely related to tumor immunity; the immune tolerance of CD4+ T cells and the inhibition of CD8+ T cell activation can promote tumor immune escape and further promote tumor progression." (PMID 34764993, 2021).
tumor (continued). "It has been reported that the immune system can profoundly influence tumor development and progression through orchestrating the suppressive effects of MDSC on CD4+/CD8+ cell activity." (PMID 34906138, 2021). "Assessing cell types in the tumor, we saw more CD8+ and CD4+ T cell infiltration, along with higher IFN-γ production from both CD4+ and CD8+ T cells in Pgdfl/flFoxp3EGFP-Cre-ERT2 versus WT mice." (PMID 34709178, 2021). "Consistent with other studies in this field, the TIME of transplanted KP tumours was more inflamed than spontaneous UPS, showing a 2-fold and 3-fold increase in CD4+ and CD8+ lymphocytes." (PMID 34242269, 2021). "A general observation of our data was that patterns of HR significance were maintained among both CD4+ and CD8+ TIL populations for anatomical subsites, indicating that tumor location is a greater discriminating factor than T-cell subset in HNSCC." (PMID 33668519, 2021). "Moreover, ADM may exert an anti-inflammatory action when released in the blood and may promote immune tolerance by direct expression in the CD4+ T cell subset and by uptake from the tumor microenvironment, as indicated by data from murine models of autoimmune disorders." (PMID 34150648, 2021). "We also reported that mice deprived of CD4+ immunosuppressive cells had an increase in the number and frequency of CD8+ T cell clones that are detected throughout the tumor, draining lymph node (dLN), and peripheral blood." (PMID 34759926, 2021). "IDO expression on tumor cells and CCL-2 secretion from microglia and macrophages in the tumor microenvironment contribute to recruiting Tregs (CD4+CD25+ FOXP3+)." (PMID 34421912, 2021). "MHC I participates in the cross-presentation of tumor antigens by DCs to CD8 T cells, while MHC II is involved in antigen presentation to CD4 T cells." (PMID 34847189, 2021). "A study using a mouse model showed that activation of OX40 signal by anti-OX40 agonistic antibody increased CD4-positive memory T cell induction, and anti-OX40 agonistic antibody also enhanced anti-tumor immune response." (PMID 34830466, 2021). "The use of CD4 and CD8 as markers for specific T cell subsets and their functions has profound implications to tumor immunology and immunotherapy." (PMID 34012443, 2021). "Flow cytometry data of T cell frequencies indicated significant activation Tem (CD44hiCD62Llo) and reduced ratios of Treg to Teff in auto-reactive CD4 T cells, however, humanized clones of CTLA-4 antibody had similar anti-tumor efficacy and improved safety." (PMID 33571254, 2021). "The expression levels of HGF in LUAD were significantly positively correlated with tumor purity, B cells, CD8+ T cells, CD4+ T cells, neutrophils, and dendritic cells." (PMID 34745947, 2021). "In genetically engineered mouse models (GEMMs), EGFR-driven tumors express higher levels of PD-L1 with a more immunosuppressive tumor microenvironment (increased FoxP3+ T-cells, decreased CD8+/CD4+ ratio)." (PMID 34488906, 2021). "After vaccination, CD4+ T cell clone directed against MAGE-A3 antigen and recognition of MAGE-A3-expressing tumor cells by CD4+ lymphocytes were observed." (PMID 33503926, 2021). "These numbers were significantly less than CD4+ and CD8+ populations in M3-9-M-Female tumours (p<0.001, one-way ANOVA with post-hoc Tukey)." (PMID 34242269, 2021). "The two groups independently reported that anti-CD25 antibodies, capable of depleting CD4+CD25+ Treg cells, led to higher tumor rejection and retarded tumor growth in normal and T cell reconstituted nude mice." (PMID 33809974, 2021). "Immunohistochemistry (IHC) highlighted tumor cells as strongly positive for CD3, CD56, CD5, CD2, CD8, CD4, CD43, T-cell restricted intracellular antigen 1 (TIA-1) and granzyme B. The proliferation index, measured by Ki-67 expression was high with 60%." (PMID 33546043, 2021).
tumor (continued). "We administered CD8+ T cell-, CD4+ T cell-, or NK cell-depleting Ab during the IFNα4 treatment of castrated Myc-CaP bearing FVB mice and measured tumor growth." (PMID 34771735, 2021). "B2M positively correlated with multiple infiltrating immune cell types, such as NK cells, CD4+ T effector memory cells (TEM), and CD8+ TEM, which play a critical role in anti-tumor response." (PMID 33658560, 2021). "A strong correlation between tumor-specific conventional CD8 T cells and cytotoxic CD4 T cells considering the expression of GZMB, GZMK and perforin was also reported." (PMID 34064410, 2021). "Moreover, decreased infiltration of monocytes, NK cell activation and T cell CD4+ naive, as well as increased infiltrating of M0 and Tregs were found in the tumor microenvironment, which may contribute to the characteristic of local immune suppression in the high-risk group." (PMID 35118063, 2021). "Five coexpressed genes (CD4, CD53, EVI2B, PLEK, and SASH3) were identified as tumor purity coexpressed genes that negatively correlated with tumor purity." (PMID 34234827, 2021). "VISTA expression was positively related with tumor-infiltrating CD68+ macrophages, CD3+ T cells, CD19+ B cells, CD4+ T-helper cells, and CD8+ cytotoxic T cells." (PMID 33237432, 2021). "Class I and class II HLA genes encode major histocompatibility complex (MHC) proteins which allow for presentation of antigenic peptides such as tumor antigens to CD8+ and CD4+ T-cell lymphocytes, respectively." (PMID 34122442, 2021). "With mfIHC, we revealed that the cytotoxic immune responses were clearly enhanced in local tumours, as significantly more CD8+ T cells and T-bet+CD4+ T cells were observed in pCR cases." (PMID 34715905, 2021). "The median density of CD3+ T cells in the tumor was 104/mm2 (1/mm2–791/mm2), 48/mm2 (0/mm2–684/mm2) for CD8+ T cells, and 12/mm2 (0/mm2–236/mm2) for CD4+ T cells, respectively." (PMID 33718143, 2021). "Tumor cells, overexpressing PD-L1 and PDL-2, develop the capacity to promote PD-1 signaling in tumor-infiltrating CD4 and CD8 T cells, therefore creating a locally immunosuppressed microenvironment." (PMID 36046088, 2021). "In this patient, CD4 and CD8 T-cell receptor repertoires were different in the CSF and tumor, indicating that ICI enhanced two pre-existing immune responses, one directed against the tumor, and another one directed against the CNS." (PMID 33897597, 2021). "Using a transgenic murine model, we demonstrated that CD4 specific TonEBP/NFAT5 knock out (CD4cre/creNFAT5flox/flox) abrogated the induction of the effector phenotype and anti-tumor efficiency of CD4+T cells following high salt treatment." (PMID 33918403, 2021). "MMP-9 has been reported to cleave and potentially degrade T-helper cell 1 (Th1)-type chemokines like CXC ligand CXCL10 and inhibit their anti-tumor outcome, including the recruitment of CD4+ T cells and CD8+ T cells, and their tumor-killing effect." (PMID 34959271, 2021). "CD4+ T cells can support and help the CD8+ T population during the anti-tumor response via the secretion of a wide range of effector cytokines." (PMID 33777750, 2021). "Mechanistically, this combination treatment with non-ablative radiation therapy and CTLA4 blockade led to increased density of tumor-infiltrating lymphocytes, increased CD8/CD4 ratio, and broadening of the TCR repertoire." (PMID 34733273, 2021). "The tumor-specific CD4+ and CD8+ T cells are directed to the tumor site, where cytotoxic T lymphocytes destroy tumor cells, whose immunogenicities have been enhanced by exposure to locally produced IFN-γ." (PMID 33807260, 2021). "CD3+ (p = 0.010), CD4+ (p = 0.045), and CD8+ (p = 0.033) TILs in the central tumor area and CD8+ TILs in the invasive margin area (p = 0.004) showed significant higher levels in LVI(+) than in LVI(−) patients." (PMID 34553029, 2021). "To understand if decreased tumor growth in MD4 mice was dependent on T cell responses, we depleted CD4+ or CD8+ T cells." (PMID 35046933, 2021).
tumor (continued). "IHC of the biopsy of the patient first revealed that most of the CD3+ T cells found in the histological section were CD4+ T cells colocalized with CD20+ cells, while CD8+ T cells were localized nearest to the tumor in the infiltrating front of neoplasia." (PMID 34868006, 2021). "The injected MoDCs migrate to the regional lymph nodes where they efficiently induce CD4+ T cell- and CD8+ T cell-mediated anti-tumor responses." (PMID 33915703, 2021). "IHC staining showed that infiltration by CD3+, CD4+, and CD8+ T cells was significantly greater in B16F10-derived tumor tissues administered the CAER than control group or single drug group." (PMID 33859948, 2021). "CD4+ T cells and CD20+ B cells generally co-occurred with CD8+ T cells at the tumor border and center, whereas CD56+ NK cells were hardly present in TNBC." (PMID 34580291, 2021). "Immunization with various vaccine platforms expressing the EBV latent proteins EBNA1, LMP1, and/or LMP2 promoted specific CD4+ and CD8+ cytotoxic responses with anti-tumor activity." (PMID 34691042, 2021). "Further, DC vaccine treatment resulted in a significant increase in CD4 and CD8 T cells in the tumor compared to PBS controls." (PMID 34445092, 2021). "Evidence from past studies indicated that CDK4 depletion reduced infiltration of CD4+FoxP3+ Tregs, and CDK4 inhibitors increased tumor immunogenicity and cytotoxic T cell–mediated clearance of tumor cells." (PMID 34309585, 2021). "This assay revealed multiple polyfunctionality-based clusters of both CD4+ and CD8+ tumor-specific reactive TILs." (PMID 34707600, 2021). "The infiltration of extensive CD4+ and CD8+ T lymphocytes was detected in the anti-PD-1-treated tumor group." (PMID 32244307, 2020). "Activation of both CD4+ and CD8+ T lymphocytes is important for an efficient immune response to destroy tumor cells." (PMID 32547541, 2020). "Our results suggested that administration of CCL7 through the intranasal pathway promoted the recruitment of cDC1 into the tumor-burdened lungs and subsequent expansion of CD8+ and CD4+ T cells in the bronchial LNs and tumor-burdened lungs." (PMID 33257678, 2020). "It has been shown that GM-CSF pretreatment led to an increase in the numbers of circulating myeloid DCs, proliferative CD4+ and CD8+ T cells, recruitment of CD8+ T cells to the tumor and a decrease in the numbers of myeloid-derived suppressor cells (MDSCs)." (PMID 32150821, 2020). "Immunogenic subclass (C2) is characterized by a massive immune cell (CD4+ T cell, CD8+ T cell, B cell, and macrophage) infiltration in tumor corresponding to immune-inflamed phenotype." (PMID 33680932, 2020). "Tumor cells were efficiently lysed by both CD8+ and CD4+ T cells, although the receptor disappeared from the surface of transiently transfected cells after a few hours." (PMID 32429316, 2020). "Accordingly, an increase in CD44hiCD62Llow/− effector T cells was detected in both CD4+ and CD8+ T cell populations in mice vaccinated with CD47KO tumor cells compared to those immunized with PBS or WT tumor cells." (PMID 31996683, 2020). "We further showed that HSD treatment resulted in an augmented frequency of IFN-γ-producing CD4+ and CD8+ T cells in the spleen and tumour of treated mice, indicating a highly activated state of these intratumoural T cells." (PMID 32265505, 2020). "For example, an increased ratio of CD8+/CD4+ CD3+ T cells and a number of IFN-γ+CD8+ CD3+ T cells can be used to predict enhanced tumour-specific T cell responses in the combination therapy of galunisertib and intestinal microbiota in HCC." (PMID 33114183, 2020). "On the other hand, radiotherapy can stimulate the complex of tumor antigen and MHC-II to be presented to CD4+ T helper cells through DC, enhancing the response of CD8+ CTL to tumor cells." (PMID 32992835, 2020).
tumor (continued). "This virus induced a higher infiltration of macrophages CD4+ and CD8+ in the tumor and longer survival in mice in comparison to HSV-1 R8308, a virus expressing the anti-inflammatory cytokine IL-10, or a control virus R3616." (PMID 33066689, 2020). "After treatment, the serum tumor marker levels along with serum MMP-2, MMP-9 and CD8+ levels in the test group decreased more remarkably, while CD4+ and CD4+/CD8+ levels increased more significantly than those in the control group (P < 0.05)." (PMID 33176740, 2020). "Previous researches had reported that infiltration of macrophage, CD4+T cell, and CD8+T cell played an important role in tumor prognosis." (PMID 31856409, 2020). "There is such a view that the interaction between CD4+ and CD8+ T lymphocyte mediates the control of tumor growth." (PMID 32847505, 2020). "IMP321 plus Montanide ISA51 VG (mannide monooleate surfactant and mineral oil) was combined with various tumor-specific peptides to activate tumor-specific CD8+ T cells and induce helper CD4+ T-cell responses." (PMID 33488573, 2020). "NK cells can indirectly contribute to tumor destruction through the activation of CD8+ cytotoxic T cells and also by promoting the differentiation of Th1 CD4+T cells through production of IFN-γ." (PMID 33050416, 2020). "IR increases the infiltration of various subtypes of T cells, including CD4+, CD8+ and Foxp3+ T cells, into the tumour area." (PMID 32284765, 2020). "Studies have shown that the presence of tumor-infiltrating lymphocytes (TILS) especially CD8+ and CD4+ T cells within the TME lead to better prognosis and response to chemotherapy in TNBC patients." (PMID 33374595, 2020). "These B cells were located in the treated tumors in close proximity to CD4+ T cells and had high MHCII expression, serving as an explanation for their overall anti-tumor activity." (PMID 33276524, 2020). "On the other hand, CD4 and CD8 single-positive T cells play crucial roles in anti-tumor immunotherapy, including immune checkpoint inhibitors." (PMID 32132638, 2020). "Because CD4+ and CD8+ T cells were the subsets most abundantly infiltrated in the tumour, we further examined these T cell compartments." (PMID 32439888, 2020). "We focused on immune cell markers (CD3, CD4, CD8, CD20) as lymphocytes are relatively regular in size and shape and we did not include CD16 and K17 in this evaluation since the myeloid and tumor cells are irregular in size and shape." (PMID 32723384, 2020). "Low and continuous administration of CTX was able to restore immune function via increase of CD4+/CD8+ T cells and depletion of T regulatory cells, not only in circulatory and splenic compartments, but also at the tumor site." (PMID 32023984, 2020). "T helper type 1 (Th1) CD4+ T cells can secrete cytokines such as IFN-γ to activate antigen-presenting cells, which in turn activate CTLs to kill tumor cells." (PMID 32104586, 2020). "Mice implanted with the parental cell line, unable to limit tumor growth, responded to TERT1, 6, and 8 by limited cytokine production: reactive CD4+ constituted 1–2%, and CD8+—2–5% of respective T cell populations." (PMID 32570805, 2020). "We also estimated densities and distribution of CD4 and CD8 T cells in formalin-fixed paraffin-embedded (FFPE) tumor sections by immunofluorescence microscopy and quantitative digital imaging." (PMID 32917858, 2020). "This study provides clear evidence that a vaccine specifically designed to deliver peptides to lymphatic organs can consistently induce both CD4+ and CD8+ T cell responses that drive tumor regression, particularly when combined with checkpoint inhibition." (PMID 33298945, 2020). "Our study highlights Yap as a broad suppressor of CD4+ and CD8+ T-cell activation and function and a key regulator of T-cell tumor infiltration and survival in cancer immunotherapy patients." (PMID 31929526, 2020).